HDAC6 (histone deacetylase 6)
Diseases named in the same sentence as HDAC6 in open-access papers (continued):
Sharing a sentence is not in itself a finding about the gene and the disease.
endothelial dysfunction (continued). "Collectively, our findings suggested that HNK treatment protects CSE against HDAC6‐mediated degradation and may constitute an alternative for preventing endothelial dysfunction and hypertensive disorders." (PMID 32755037, 2020). "In our previous study we showed that the atherogenic stimulus OxLDL triggers endothelial dysfunction by downregulating expression of atheroprotective enzyme endothelial cystathionine lyase γ, which produces vasoactive hydrogen sulfide through activation of its transcriptional regulator HDAC6." (PMID 34220539, 2021). "In conclusion, we demonstrated for the first time that HNK‐mediated HDAC6 inhibition induces acetylation‐dependent CSE stabilization, thereby attenuating AngII‐induced hypertension and endothelial dysfunction." (PMID 32755037, 2020). "Further, blocking HDAC6 activity directly with tubacin or indirectly by blocking its post-translational modifier NEDD8 with MLN4924, provides options for new therapeutic strategies to treat or reverse endothelial dysfunction and atherosclerosis." (PMID 34220539, 2021). "GLP-1, however, engages the GLP-1R/ERK1/2/HDAC6 axis to modulate downstream transcriptional activity, it lowers intracellular ROS, reduces Akt and ERK1/2 phosphorylation, restores HDAC6 expression, and thereby alleviates endothelial dysfunction and excessive autophagy." (PMID 41019986, 2025). "That study exposes a limitation of our own, in that the protective effect of tubacin against endothelial dysfunction and atherogenesis could be independent of HDAC6 inhibition." (PMID 34220539, 2021).
pulmonary fibrosis (14 papers, 2016 to 2025). Chronic progressive interstitial lung disorder characterized by the replacement of the lung tissue by connective tissue, leading to progressive dyspnea, respiratory failure, or right heart failure. "Masson′s trichrome and hematoxylin-eosin staining demonstrated that HDAC6 deficiency protected mice from BLM-induced pulmonary fibrosis." (PMID 39122680, 2024). "While it may be tempting to speculate from these results that HDAC6 is minimally involved in the cavernous fibrosis process, HDAC6 has been implicated as an important factor in pulmonary fibrosis." (PMID 39790566, 2024). "Tubastatin ameliorates lung fibrosis by targeting TGFβ-PI3K-Akt pathway via an HDAC6-independent mechanism." (PMID 39544928, 2024). "Mechanistic study reveals that downregulation of CYLD underlies the crosstalk between EMT and ciliary homeostasis by inactivating histone deacetylase 6 (HDAC6) during pulmonary fibrosis." (PMID 39122680, 2024). "The same study also identified the suppression of HDAC6 inhibitors against lung fibrosis in mouse models." (PMID 39412062, 2024). "In contrast to all other Class II HDACs, isoform-selective inhibitors have been developed for HDAC6 and not only evaluated in cancer but also lung fibrosis." (PMID 35626663, 2022). "On the other hand, selective inhibition of HDAC3, HDAC6 or HDAC8 has recently been demonstrated to exert remarkable therapeutic effects in the bleomycin mouse model of lung fibrosis." (PMID 35626663, 2022). "Another specific histone deacetylase 6 inhibitor, CY-1215, also known as ricolinostat, has reported many other effects such as anti-cancer, improvement of pulmonary fibrosis, and alleviation of peripheral neuropathy." (PMID 31183000, 2019). "We investigated the role of HDAC6 and the effect of Tubastatin in a murine model of bleomycin-induced pulmonary fibrosis." (PMID 29045477, 2017). "Moreover, our group has recently demonstrated HDAC6 inhibition as an effective treatment against TGF-β-induced idiopathic pulmonary fibrosis, we believe taking advantage of this new property of HDAC6 will boost our strategy towards treating the disease." (PMID 40013582, 2025). "Our previous study successfully synthesized a selective HDAC6 inhibitor, J22352, for pulmonary fibrosis; however, the treatment efficacies on BMF remain unclear." (PMID 40750768, 2025). "Our previous study and others revealed that CYLD is a HDAC6 inactivator, we speculate that CYLD regulates EMT program and ciliary homeostasis by inactivating HDAC6 during pulmonary fibrosis." (PMID 39122680, 2024). "In the normal conditions, CYLD inactivates HDAC6 to promote primary ciliary homeostasis as well as inhibit EMT program; however, during pulmonary fibrosis, CYLD deficiency relieves its inhibitory interaction with HDAC6, thereby leading to primary disassembly and the EMT program." (PMID 39122680, 2024). "Therefore, we set out to investigate whether inhibition of HDAC6 can attenuate pulmonary fibrosis in experimental models." (PMID 29045477, 2017). "Collectively, these results identify a pivotal role for the CYLD/HDAC6 signaling in regulating the reciprocal interplay between the EMT program and ciliary homeostasis during pulmonary fibrosis." (PMID 39122680, 2024). "In this study, we identify a critical role for CYLD/HDAC6 signaling in regulating the reciprocal interplay between the EMT program and primary cilia during pulmonary fibrosis." (PMID 39122680, 2024). "HDAC6 has been shown to upregulate the TGF‐β1‐Smad2/3 and ‐Smad7 signalling pathways, leading to renal and pulmonary fibrosis." (PMID 39232846, 2024). "Thus, we examined whether HDAC6 is involved in pulmonary fibrosis." (PMID 39122680, 2024). "Until now, most of the agents developed have selectivity for HDAC3, HDAC6 and HDAC8 and have been or are still currently evaluated in preclinical studies for cancer and lung fibrosis." (PMID 35626663, 2022).
pulmonary fibrosis (continued). "Our data suggest that Tubastatin ameliorates pulmonary fibrosis, by targeting the TGFβ-PI3K-Akt pathway, likely via an HDAC6-independent mechanism." (PMID 29045477, 2017). "However, the role of HDAC6 in pulmonary fibrosis is unknown." (PMID 29045477, 2017). "In summary, this work demonstrates that HDAC6 expression is deregulated in IPF lungs and in a murine model of bleomycin-induced pulmonary fibrosis." (PMID 29045477, 2017). "Our data suggests that Tubastatin ameliorates pulmonary fibrosis, by targeting the TGFβ-PI3K-Akt pathway, likely via an HDAC6-independent mechanism." (PMID 29045477, 2017). "In this study, we found that the acetylated α-tubulin was significantly reduced but the level of HDAC6 was not changed during pulmonary fibrosis." (PMID 39122680, 2024). "Lead compounds J27644 (4, HDAC6/8 inhibitor, IC50s 13 and 151 nM, respectively) and 5 (HDAC6 inhibitor, IC50 = 62 nM) reduced α-SMA and Col1a1 protein levels and efficiently modulated fibroblast survival, countering pulmonary fibrosis." (PMID 39766311, 2024). "Tubastatin, a “selective” HDAC6 inhibitor, inhibits TGF-β1-induced type-1 collagen expression in lung fibroblasts, and reduces type-1 collagen expression in murine bleomycin-induced pulmonary fibrosis." (PMID 29045477, 2017). "Although a few studies investigated the effect of non-selective pan-HDAC inhibitors as well as class I HDAC inhibitors on pulmonary fibrosis, the effects of selective inhibition of HDAC6 on pulmonary fibrosis has never been reported." (PMID 29045477, 2017). "However, homozygous Hdac6(−/−) knockout mice were not protected against bleomycin-induced lung fibrosis despite pronounced hyperacetylation of α-tubulin." (PMID 35626663, 2022). "In contrast, HDAC6 KO mice were not protected from bleomycin-mediated pulmonary fibrosis." (PMID 29045477, 2017). "Together, these results suggested that tubastatin might have ameliorated bleomycin-induced lung fibrosis by targeting the PI3K-AKT pathway, likely through an HDAC6-independent mechanism, and that tubastatin might have significant off-target effects aside from HDAC6." (PMID 35626663, 2022). "As an HDAC6 inhibitor, tubastatin reversed the BLM-induced LC3B inhibition, S6k phosphorylation and HIF-1α expression, which ameliorated lung fibrosis by inhibiting the PI3K-Akt pathway in WT mice, but not in HDAC6 KO mice." (PMID 32724454, 2020).
Stroke (14 papers, 2016 to 2026). Sudden impairment of blood flow to a part of the brain due to occlusion or rupture of an artery to the brain. "Pharmacological or gene inhibition experiments on HDAC6 confirmed the block caused by stroke, indicating that the normal function of HDAC6 is necessary for the efficacy of rehabilitation treatment after stroke." (PMID 32963637, 2020). "Meanwhile, the aberrant phenotypes in dendritic maturation correlate with symptomatic impairment of functional recovery of the brain, which is pathologically linked to aberrant nuclear translocation of HDAC6 after stroke." (PMID 30999900, 2019). "To determine whether HDAC6 expression is implicated in stroke, we induced ischemic stroke in the cortex, where HDAC6 is highly expressed, using the photothrombotic model." (PMID 35585040, 2022). "HDAC6 gene mutation is closely related to large-vessel stroke, however, the role and mechanism of HDAC6 on experimental stroke-induced brain injury still remains unclear." (PMID 31231583, 2019). "Modelling analyses demonstrated that animals receiving HDAC6 inhibitors during the hyperacute phase of stroke had significantly better functional outcomes, whereas sub-acute HDAC6 inhibition impaired recovery." (PMID 41549345, 2026). "This article aimed to quantify the impact of pharmacologically inhibiting HDAC6 on cerebral infarction size and neurological function within in vivo stroke models." (PMID 41549345, 2026). "This was upheld in sub-analyses comparing different species, and groups receiving HDAC6 inhibitors shortly after stroke, or after a 24 h delay." (PMID 41549345, 2026). "In particular, HDAC2 and HDAC6 are involved in the stroke-induced death of neurons in the ischemic brain." (PMID 34680562, 2021). "During the first two weeks after the photothrombotic stroke, HDAC6 was upregulated in the neurons not only in the penumbra, but also in the contralateral cerebral cortex, where it appeared in the neuronal nuclei." (PMID 34680562, 2021). "Researchers injected them into the vein of mice stroke models and found that they can promote functional recovery of stroke by inhibiting histone deacetylase 6 via miR-26a." (PMID 34588957, 2021). "The selective HDAC6 inhibitors tubastatin A or HPOB promoted post-stroke regeneration of the mouse brain." (PMID 34680562, 2021). "In summary, our research for the first time confirms that USC‐Exos exalt both proliferation and neuronal differentiation of cultured NSCs subjected to OGD/R, and promote neurogenesis in rats after stroke, potentially through miR‐26a/HDAC6 axis." (PMID 31667951, 2020). "HDAC6 interference protected mice against experimental stroke-induced brain injury via Nrf2/HO-1 pathway." (PMID 31231583, 2019). "In this study, we also constructed a model of cerebral ischemia-reperfusion in mice, and studied the role and mechanism of HDAC6 on experimental stroke-induced brain injury." (PMID 31231583, 2019). "Pharmacological and genetic experiments further emphasized the requirement of HDAC6 in rehabilitation therapy induced therapeutic benefits after stroke." (PMID 30999900, 2019). "We found the expression of HDAC6 is predominant in cytosol of control animals, but it translocated substantially into the nucleus after stroke." (PMID 30999900, 2019). "More importantly, we provide direct evidence showing the proper function of HDAC6 is required for rehabilitation therapy induced therapeutic benefits after stroke." (PMID 30999900, 2019). "The study was to investigate the role and mechanism of Histone deacetylase 6 (HDAC6) on experimental stroke-induced brain injury." (PMID 31231583, 2019). "Together, the results collected from our biochemical analyses revealed that the aberrant nuclear distribution of HDAC6 after stroke limits its accessibility to its cytosolic substrates, including acetylated α-tubulin." (PMID 30999900, 2019). "Despite a small evidence base, findings suggest that HDAC6 inhibition within 24 h of stroke onset may improve outcomes." (PMID 41549345, 2026).
Stroke (continued). "Studies employing randomised controlled trial principles, and detailed assessment of the molecular and physiological mechanisms underpinning reported cytoprotection are warranted to assess clinical potential pharmacological HDAC6 inhibition to improve stroke management." (PMID 41549345, 2026). "Furthermore, studies on HDAC6 have shown that inhibiting HDAC6 can protect mice from experimental stroke-induced brain injury by regulating oxidative stress through activation of the NRF2/HO-1 pathway." (PMID 40258841, 2025). "In addition, HDAC6 has been reported to be involved in acute cardiomyocyte injury, kidney disease, spinal cord injury, and stroke." (PMID 33744850, 2021). "Another selective HDAC6 inhibitor tubacin increases eNOS expression in vivo improving endothelial function in diabetic db / db mice and significantly reduces ischemic brain damage in a mouse stroke model." (PMID 34680562, 2021). "Furthermore, HDAC6 is crucial as a target for neuroprotection and neuroregeneration in traumatic brain injury, stroke, and neurodegenerative disorders 11-14." (PMID 33162824, 2020). "Our current findings might provide a feasible therapeutic strategy that targets HDAC6 for promoting functional recovery toward the patients with stroke in clinic." (PMID 30999900, 2019). "Subsequent biochemical analyses revealed an aberrant nuclear translocation of HDAC6 that leads to the hyper-acetylation of α-tubulin (an indication of over-stabilized microtubules) after hypoxic challenge was observed at different time points after stroke." (PMID 30999900, 2019). "Our major finding about the proper function of HDAC6 is required for functional recovery of the brain might provide a feasible therapeutic strategy for the unmet need of stroke therapy in clinic." (PMID 30999900, 2019). "Furthermore, the mimicry experiments with either pharmacological or genetic suppression of HDAC6, phenocopied the stroke induced retardation in dendritic maturation of newly generating neurons in vivo." (PMID 30999900, 2019). "Individual studies report that specifically inhibiting HDAC6 may improve stroke outcomes." (PMID 41549345, 2026). "USC‐Exos could reduce the expression of HDAC6 induced by stroke models." (PMID 31667951, 2020). "Together, our current study unravels that dysfunction of HDAC6 contributes to stroke induced deficits in neurogenesis and provides an innovative therapeutic strategy that targets HDAC6 for promoting functional recovery toward the patients with stroke in clinic." (PMID 30999900, 2019).
cholangiocarcinoma (13 papers, 2019 to 2023). A carcinoma that arises from the intrahepatic biliary tree (intrahepatic cholangiocarcinoma) or from the junction, or adjacent to the junction, of the right and left hepatic ducts (hilar cholangiocarcinoma). "For instance, in cholangiocarcinoma (CCA) cell lines, miRNA‐433 upregulation caused a reduction in HDAC6 levels, inhibited the proliferation, colony formation ability, cellular migration, and stimulated ciliogenesis." (PMID 35976177, 2022). "Inhibition of HDAC6 restores ciliogenesis and suppresses the proliferation of cancer cells, including glioblastoma, cholangiocarcinoma, and chondrosarcoma." (PMID 37780208, 2023). "This fact was also demonstrated in cholangiocarcinoma, where cells that presented overexpression of HDAC6 did not present a primary cilium, but the ciliary structure was recovered after HDAC6 inhibition." (PMID 34073238, 2021). "In cholangiocarcinoma cells, overexpression of HDAC6 reduces ciliogenesis, whereas knocking down or inhibiting HDAC6 prevents ciliary breakdown and increases the number of ciliated cancer cells." (PMID 33915983, 2021). "miR-433, targeting HDAC6, decreased the malignant phenotype of cholangiocarcinoma." (PMID 36076996, 2022). "Recently HDAC6 inhibitors were reported to restore PC and inhibit cholangiocarcinoma." (PMID 34082797, 2021). "Treatment with an HDAC6 inhibitor such as Tubastatin-A increases the frequency of ciliated cholangiocarcinoma cells and decreases their proliferation, and ablation of cilia by disruption of key ciliogenesis gene Intraflagellar transport protein 88 (IFT88) abolishes this antiproliferative effect." (PMID 33915983, 2021). "Butyrate enhanced the anti-cancer effects of HDAC6 inhibitors in cholangiocarcinoma (CCA) by decreasing Zeb1 expression." (PMID 36076996, 2022). "HDAC6 inhibition with pharmacological or genetic approaches has been used to induce PC restoration and reverse the malignant phenotype in cholangiocarcinoma (CCA)." (PMID 37510333, 2023). "TBA has been shown to restore cilia expression in cholangiocarcinoma and prevent the deciliation of RPE1 by HDAC6 overexpression." (PMID 31369591, 2019). "In cholangiocarcinoma cases lacking primary cilia, inhibition of HDAC6, a primary cilia disassembly factor, restored primary cilia formation and inhibited cholangiocarcinoma growth." (PMID 37900915, 2023).